SHBG (sex hormone binding globulin)
Diseases named in the same sentence as SHBG in open-access papers (continued):
Sharing a sentence is not in itself a finding about the gene and the disease.
Insulin resistance (continued). "Third, insulin resistance in abnormal fat distribution and T2DM result in a decrease in sex hormone-binding globulin (SHBG), secondary to a decrease in TT." (PMID 38260153, 2023). "Insofar insulin resistance constitutes on one the most prominent hallmarks of EMS, the potential of SHBG treatment to restore insulin signalling in EMS-affected ASC has been further investigated." (PMID 37697311, 2023). "Therefore, SHBG may be considered as a surrogate marker of hepatic insulin resistance." (PMID 35140785, 2022). "Low concentrations of sex hormone binding globulin (SHBG) are prevalent in T2DM, impaired glucose tolerance, insulin resistance, and obesity." (PMID 36457554, 2022). "Insulin resistance might contribute to hyperandrogenism by several mechanisms: insulin acts synergistically with luteinizing hormone to improve androgen production, and high levels of insulin reduce circulating SHBG levels, thereby increasing the bioavailability of testosterone." (PMID 34081616, 2021). "Recently, sex hormone binding globulin (SHBG) and fetuin-A (AHSG) have been shown to play an important regulatory role in insulin resistance, and can thus represent promising targets for future therapeutics." (PMID 33536069, 2021). "Furthermore, an increase in circulating levels of testosterone along with low levels of sex-hormone-binding globulin (SHBG) is associated with cardiovascular disease, insulin resistance, and visceral obesity, while cardiovascular morbidity and mortality may be correlated with major depression." (PMID 33802106, 2021). "Aquatic exercise safely improved body composition, reduced insulin resistance, and positively affected the sex hormones DHEA-S and SHBG as well as blood lipid profiles." (PMID 33918160, 2021). "The SHBG and HDL-C levels significantly increased, and insulin resistance significantly decreased in our exercise, compared with the control group." (PMID 33918160, 2021). "TT levels are subjected to variations related to the circulating levels of Sex-Hormone Binding Globulin (SHBG), which is produced in the liver and can be mildly reduced under states of obesity, insulin resistance, and NAFLD." (PMID 34244582, 2021). "Aquatic exercise is also considered effective in reducing insulin resistance and metabolic and cardiovascular risks by increasing DHEA-S and SHBG levels." (PMID 33918160, 2021). "The outcomes assessed included BMI and waist circumference, fasting serum insulin levels and insulin resistance as assessed by HOMA-IR, and androgenic status including serum total testosterone and sex hormone-binding globulin (SHBG) concentrations." (PMID 32442310, 2020). "This study showed the beneficial effects of vitamin K (MK‐7) on the reduction of insulin resistance, body fat mass, and triglycerides, and increasing skeletal muscle mass, serum DHT, and SHBG levels in patients with PCOS." (PMID 33133563, 2020). "Serum/plasma concentrations of glucose, insulin (with the calculation of homeostatic model assessment insulin resistance—HOMA-IR), estradiol, total testosterone, sex hormone-binding globulin (SHBG) and sclerostin were measured." (PMID 32592042, 2020). "Dietary components seem to play a role in the regulation of androgens and SHBG concentrations in PCOS subjects, and it is possible that insulin resistance is involved in this process." (PMID 32927680, 2020). "One meta-analysis of eight studies in PCOS adult women recommended a hypocaloric diet for the reduction of BMI, treatment of PCOS with insulin resistance, prevention of high LDL-C, increasing the levels of FSH and SHBG, and decreasing the level of TG level." (PMID 32429890, 2020). "Results showed the beneficial effect of 8‐week supplementation with Menaquinone‐7 on insulin resistance, fat mass, skeletal muscle, and serum levels of triglyceride, DHT, and SHBG in the study participants." (PMID 33133563, 2020).
Insulin resistance (continued). "This study highlights the beneficial effects of MK‐7 on insulin resistance, fat mass, skeletal muscle, and serum levels of triglyceride, DHT, and SHBG in PCOS patients." (PMID 33133563, 2020). "A decrease of the SHBG level itself is one of the markers of PCOS, interconnected with insulin resistance and HA." (PMID 32545404, 2020). "It was found that insulin resistance (HbA1c, HOMA-IR) and inflammation (hsCRP, IL-6) circulating biomarkers decreased, while reproductive biomarkers (LH, FSH, SHBG) increased significantly." (PMID 31440472, 2019). "Indeed, there may be a bidirectional relationship between SHBG, insulin resistance and adiposity." (PMID 30925463, 2019). "However, after menarche, no directional influences between SHBG, adiposity and insulin resistance were found, suggesting that observational associations between SHBG, adiposity and insulin resistance in pubertal children may be subject to confounding." (PMID 30925463, 2019). "Conversely, the increment of SHBG levels observed during the CC treatment may reflect a direct estrogen stimulating production of that protein at hepatic levels, possibly combined with a mild effect obtained by insulin-resistance improvement shown in this phase." (PMID 28886024, 2017). "This fact can be explained by insulin resistance and hyperinsulinemia in overweight/obese patients with persistent anovulation and PCOS, which augments ovarian/adrenal androgen production and SHBG suppression, thereby increasing androgen bioavailability." (PMID 26000003, 2015). "By stimulating ovarian androgen production and decreasing serum sex hormone-binding globulin (SHBG) concentrations, hyperinsulinemic insulin resistance leads to hyperandrogenism and anovulation." (PMID 25815012, 2015). "Other top predictors included markers of insulin resistance and the IGF pathway (insulin, IGFBP1, uric acid), sex hormones (free estradiol, SHBG), lipid-soluble micronutrients (vitamin D3, lycopene, CoQ10, alpha-tocopherol) and markers of inflammation (CRP)." (PMID 22912885, 2012). "Compared to IL-6 and TNF-α, which indicate chronic inflammation, SHBG is a negative marker that is it decreases, worsening insulin resistance and hyperandrogenism." (PMID 40385768, 2025). "In addition, our data confirm the usefulness of the TyG index as an initial assessment of insulin resistance, which should be confirmed by assessing the HOMA-IR value or SHBG concentration." (PMID 40430120, 2025). "Insulin resistance or hyperinsulinemia—often resulting from a higher BMI—can lead to a decrease in the concentration of sex hormone-binding globulin (SHBG) through a negative feedback mechanism." (PMID 40431387, 2025). "Insulin resistance, a key feature of metabolic syndrome, results in compensatory hyperinsulinemia, increased IGF-1 secretion, and reduced levels of sex hormone-binding globulin (SHBG), thereby increasing free androgen bioavailability and amplifying inflammatory pathways." (PMID 40868844, 2025). "Further supporting this, SHBG overexpression in transgenic mice protects against high-fat (with carbohydrate) diet (HFD)-induced obesity and insulin resistance, improving glucose tolerance, lowering insulin levels, and attenuating increases in leptin and resistin levels." (PMID 41586225, 2025). "This indicates that low SHBG expression may suppress the PI3K/AKT pathway, thereby contributing to the development of insulin resistance." (PMID 38848344, 2024). "Insulin resistance leads to elevated insulin levels, resulting in increased secretion of insulin-like growth factor-1 (IGF-1), decreased production of sex hormone-binding globulin (SHBG), and increased levels of free sex hormones." (PMID 39469573, 2024). "In non-diabetic cases the serum levels of SHBG correlated with serum insulin and insulin resistance." (PMID 39014506, 2024).
Insulin resistance (continued). "In addition, C-reactive protein (CRP) (p < 0.001), homeostasis model assessment–insulin resistance (HOMA-IR) (p < 0.05), and fasting blood glucose (p < 0.01) were elevated whilst PCOS women had a lower SHBG (p < 0.001)." (PMID 39858399, 2024). "While it is possible that elevated levels of specific hormones, such as SHBG, could offer protection against GDM, the primary contributors to the development of GDM are insulin resistance and other metabolic factors, including HbA1c, TG, FFA, and BMI." (PMID 39876919, 2024). "Notably, a correlation emerged between factors of glucose metabolism and insulin resistance (glucose, insulin, HbA1C, HOMA-IR), with SHBG (β: −0.108) at the initial assessment being negatively associated with depressive symptomatology in the CDI." (PMID 39519542, 2024). "Significant relation between SHBG level and Mets was detected in the subjects aged ≥ 60 years, without insulin resistance, with normal BMI, and with eGFR ≥90 mL/min per 1.73m2 (p < 0.05)." (PMID 38988998, 2024). "In fact, in vitro studies indicate that SHBG may down-regulate the PI3K/AKT pathway involved in the development of local and systemic insulin resistance." (PMID 37405618, 2023). "Although SHBG’s main function is to bind sex steroids to reduce free sex hormone levels, SHBG has also been found to link inversely to insulin resistance independent of sex hormone levels." (PMID 37573326, 2023). "This suggests that the superior effectiveness of EX in this patient population in terms of improving reproductive function may be due to its effects on SHBG, FSH, and DHEA-S levels, potentially indirectly by lowering insulin resistance." (PMID 37002532, 2023). "Furthermore, we found that application of SHBG to EMS SAT increased the protein level of Glut-4, suggesting a possible alleviation of insulin resistance and improvement of the glucose uptake capacity." (PMID 38146533, 2023). "Additionally, SHBG concentrations are modulated by various conditions, including puberty, polycystic ovary syndrome (PCOS), insulin resistance, and disorders of glucose and lipid metabolism." (PMID 38317710, 2023). "Although our study did not consider the measurement of insulin resistance, leptin, and SHBG (to calculate free T), wc, BMI, and estradiol levels were elevated, supporting this pathophysiologic pathway." (PMID 36282472, 2023). "According to Qu and Donnelly, there is a negative correlation between circulating SHBG levels and markers of insulin resistance." (PMID 37405618, 2023). "SCH was associated with a decrease in glucose disposal, but an increase in serum SHBG, total cholesterol (TC), low-density lipoprotein (LDL) cholesterol, and total triglyceride (TG) levels, weight, and insulin resistance in the general population, particularly in women." (PMID 37635968, 2023). "By exerting the effect on ovarian androgen synthesis and decreased synthesis of sex hormone binding globulin (SHBG), insulin resistance may be responsible for the development of hyperandrogenism." (PMID 36235688, 2022). "The probability of insulin resistance occurrence for SHBG concentration 26.1 nmol/L (the lower normal range) was 61.6% (95% CI: 57.4%–65.8%)." (PMID 35140785, 2022). "In addition, the PCOS group had elevated fasting insulin levels, Homeostatic Model Assessment for Insulin Resistance (HOMA-IR), and lower sex hormone-binding globulin (SHBG) and Matsuda index levels (to measure insulin sensitivity) than controls (p ≤ 0.04)." (PMID 35628399, 2022). "Despite limited studies providing mechanistic insights linking SHBG and CKD, inflammation and insulin resistance could mediate this link." (PMID 36601008, 2022). "Moreover, women with PCOS have insulin resistance that is thought to be intrinsic to the syndrome, which contributes to a worsening of the metabolic pathophysiology of PCOS and reduces SHBG levels." (PMID 36235799, 2022).
Insulin resistance (continued). "Levels of SHBG decrease in the presence of weight gain, and of insulin resistance and hyperinsulinism, regardless of weight." (PMID 33918160, 2021). "Patients underwent blood tests for determination of follicle-stimulating hormone (FSH), luteinizing hormone (LH), total testosterone, DHEA-S, estradiol, of sex hormone-binding globulin (SHBG), fasting glucose, insulin, Homeostatic Model Assessment of Insulin Resistance (HOMA-IR), and lipid profile." (PMID 32967289, 2020). "An in vivo animal study using SHBG transgenic mice compared with wild type mice found that overexpression of SHBG protects against high fat diet (HFD) induced obesity and insulin resistance, as evidenced by lower glucose profiles during glucose tolerance tests and insulin tolerance tests." (PMID 33139661, 2020). "A study using liver samples from nondiabetic obese patients with NAFLD demonstrated that triglycerides accumulate in the liver and insulin resistance (assessed by homeostatis model assessment, HOMA-IR) was inversely related to SHBG mRNA and to HNF4 α mRNA as well as to circulating SHBG levels." (PMID 33139661, 2020). "Mutations of INSR should be kept in mind in patients with severe insulin resistance but without metabolic dyslipidemia, low SHBG level and hepatosteatosis." (PMID 32018348, 2020). "Our results suggest that in early puberty, decline in SHBG predicts development of insulin resistance, independent of adiposity." (PMID 30925463, 2019). "Notably, HIV-infected men in the MACS have higher SHBG levels than HIV-uninfected men, despite having more insulin resistance and diabetes." (PMID 32128321, 2019). "Those with a raised FAIs may reflect the role of SHBG that is reduced by insulin resistance that will increase FAI, and that may in turn increase insulin resistance." (PMID 28620242, 2017). "PSA levels are regulated by androgens, and testosterone levels are lower than normal in men with type 2 diabetes, and it can be due to a decrease in SHBG, and there is a negative relationship between insulin resistance and serum PSA levels." (PMID 27921025, 2016). "In patients with PCOS, afamin correlated significantly with homeostatic model assessment-insulin resistance (HOMA-IR), fasting glucose, BMI, FTI, and SHBG (P<0.001), but in a multivariate linear model, only HOMA-IR remained significantly associated with afamin (P=0.001)." (PMID 24928911, 2014). "Obese women with PCOS had a significantly higher total T level, FAI, fasting insulin, insulin resistance index as determined by homeostasis model assessment for insulin resistance, and lower SHBG levels than the nonobese women with PCOS (P < .05)." (PMID 24694334, 2014). "Further research from cell, animal, and human experiments is needed to shed etiologic light on the interplay of adiposity, insulin resistance, inflammation, the IGF axis, SHBG, and sex hormones, among other biologic intermediaries in the association of earlier menarche with diabetes." (PMID 24438044, 2014). "The association between SHBG and hypertension was stronger than the association between HOMA-IR (surrogate of insulin resistance) and hypertension in men but not in women." (PMID 23594436, 2013). "Patients with insulin receptor defects also differ biochemically from other types of insulin resistance by displaying elevated adiponectin, IGFBP1, and SHBG, which are all commonly suppressed in common insulin resistance or lipodystrophy-associated severe insulin resistance." (PMID 23766565, 2013). "In a prospective study on Japanese-American subjects who were followed for 3 years, however, SHBG did not correlate with insulin resistance in either men or women, suggesting ethnic differences." (PMID 29043159, 2013).
Insulin resistance (continued). "Of interest, diabetes reportedly protects against the development of prostate cancer, since it is testosterone-dependent and testosterone deficiency is common among men with diabetes secondary to low levels of sex hormone-binding globulin (SHBG) and partially because of insulin resistance." (PMID 22448244, 2012). "Therefore, the present study aimed to estimate the cut-off value for these indices discriminating the IR based on the homeostatic model assessment for insulin resistance (HOMA-IR) and sex hormone binding globulin (SHBG) levels established previously in Caucasian women with PCOS." (PMID 41752690, 2026). "The same authors found a negative association between C‐reactive protein (a marker of non‐alcoholic fatty liver disease) and SHBG independent of homoeostatic model assessment for insulin resistance, alcohol consumption, haemoglobin A1C and waist‐hip ratio in women with PCOS." (PMID 39996383, 2025). "Moreover, studies using an insulin-resistant gestational diabetes model demonstrated that β-carotene elevates sex hormone binding globulin (SHBG) expression, which subsequently enhances GLUT4 expression, leading to improved glucose uptake and reduced insulin resistance." (PMID 41515170, 2025). "Furthermore, a negative correlation was observed between insulin resistance and sex hormone-binding globulin (SHBG) levels." (PMID 40868057, 2025). "In the context of SHBG, a negative significant relationship with metabolic markers like BMI, weight, or insulin resistance (HOMA2) could indicate that worsening metabolic health (increased adiposity, insulin resistance) is associated with lower levels of SHBG." (PMID 39768643, 2024). "Although FHA patients with PCOM revealed higher HOMA index levels for insulin resistance, this might not completely explain the difference in SHBG levels." (PMID 38592037, 2024). "Probiotic and synbiotic supplementation showed significant improvements in insulin resistance (reductions in HOMA-IR, fasting glucose, and insulin), lipid profiles (decreased LDL and triglycerides; increased HDL), and hormonal balance (increased SHBG, decreased total testosterone)." (PMID 39599701, 2024). "SHBG may inhibit the phosphatidylinositol 3-kinase (PI3K)/protein kinase B (AKT) pathway, which plays a role in the development of both local and systemic insulin resistance (IR)." (PMID 39768643, 2024). "Therefore, in many cases the low SHBG level would not allow for the diagnosis of insulin resistance but, on the other hand, the likelihood of false positive results is low." (PMID 36968815, 2023). "SHBG, on the other hand, had a higher value than those without insulin resistance." (PMID 36829146, 2023). "However, the original GWAS of SHBG in our analysis by the Neale lab using UK biobank data was only adjusted for sex, but not for BMI or insulin resistance." (PMID 34207127, 2021). "Therefore, it appears that the reduction in body fat mass in the intervention group could improve insulin resistance, which might lead to the decreased DHT and increased SHBG." (PMID 33133563, 2020). "An increase in the level of HNF-4α promotes the synthesis of SHBG in the liver, while chronic inflammatory factors may indirectly reduce the level of HNF-4α, which results in a decrease in the production of SHBG and exposure to insulin resistance." (PMID 32992734, 2020). "Other work has also reported that PCOS is more common among young women with biopsy-proven NAFLD and decreased plasma SHBG levels, regardless of overweight/obesity status but insulin resistance and dyslipidaemia showed a reverse relationship with plasma levels of SHGB in women with PCOS." (PMID 33139661, 2020). "After menarche, no directional effect was found between SHBG and insulin resistance or adiposity." (PMID 30925463, 2019).